ATF7 (activating transcription factor 7)
Description:
Stress-responsive chromatin regulator that plays a role in various biological processes including innate immunological memory, adipocyte differentiation or telomerase regulation. In absence of stress, contributes to the formation of heterochromatin and heterochromatin-like structure by recruiting histone H3K9 tri- and di-methyltransferases thus silencing the transcription of target genes such as STAT1 in adipocytes, or genes involved in innate immunity in macrophages and adipocytes (By similarity). Stress induces ATF7 phosphorylation that disrupts interactions with histone methyltransferase and enhances the association with coactivators containing histone acetyltransferase and/or histone demethylase, leading to disruption of the heterochromatin-like structure and subsequently transcriptional activation (By similarity). In response to TNF, which is induced by various stresses, phosphorylated ATF7 and telomerase are released from telomeres leading to telomere shortening. Also plays a role in maintaining epithelial regenerative capacity and protecting against cell death during intestinal epithelial damage and repair (By similarity). [Isoform 4]: Acts as a dominant repressor of the E-selectin/NF-ELAM1/delta-A promoter. [Isoform 5]: Acts as a negative regulator, inhibiting both ATF2 and ATF7 transcriptional activities. It may exert these effects by sequestrating in the cytoplasm the Thr-53 phosphorylating kinase, preventing activation.
Synonyms: ATFA
Tractability: PROTAC: UniProt records ubiquitination sites on it; ubiquitination databases record sites on it.
Gene: Protein-coding gene on chromosome 12 (53,507,856 to 53,626,410, reverse strand). Ensembl gene ENSG00000170653.
Subcellular location: Nucleus; Nucleus, nucleoplasm; Chromosome, telomere; Cytoplasm (Isoform 5)
Subcellular location (Human Protein Atlas): Cytosol; Nucleoplasm
Gene Ontology:
Molecular function: enzyme binding; mitogen-activated protein kinase binding; protein binding; RNA polymerase II cis-regulatory region sequence-specific DNA binding; sequence-specific double-stranded DNA binding; transcription coactivator binding; cAMP response element binding; DNA-binding transcription factor activity; DNA-binding transcription factor activity, RNA polymerase II-specific
Biological process: positive regulation of transcription by RNA polymerase II; regulation of DNA-templated transcription; regulation of transcription by RNA polymerase II
Cellular component: cytoplasm; nucleus; RNA polymerase II transcription regulator complex; chromatin; chromosome, telomeric region; nucleoplasm
Genetic constraint (gnomAD): Loss-of-function variants: 10 observed, 43.38 expected, observed/expected ratio (o/e) 0.23, 90% interval 0.14 to 0.39. The upper end of that interval is the gene's LOEUF score, 0.39, which puts it in group 1 of 6, group 1 being the genes least tolerant of losing a copy. Missense variants: 458 observed, 616.9 expected, observed/expected ratio (o/e) 0.74, 90% interval 0.69 to 0.8. Synonymous variants: 196 observed, 227.87 expected, observed/expected ratio (o/e) 0.86, 90% interval 0.76 to 0.97.
Homologues: Orthologues: chimpanzee ATF7 (100% identical), macaque ATF7 (99% identical), pig ATF7 (99% identical), mouse Atf7 (98% identical), rabbit ATF7 (97% identical), rat Atf7 (97% identical), dog ATF7 (96% identical), guinea pig ATF7 (83% identical), tropical clawed frog atf7 (79% identical), zebrafish atf7a (72% identical), Caenorhabditis elegans atf-7 (22% identical). Paralogues in human: ATF2 (58% identical), CREB5 (47% identical).